INS (insulin)
Diseases named in the same sentence as INS in open-access papers (continued):
Sharing a sentence is not in itself a finding about the gene and the disease.
Hepatic steatosis (continued). "Most studies with 3,5-T2 demonstrated amelioration in glucose tolerance, insulin sensitivity and liver steatosis." (PMID 30072951, 2018). "The molecular mechanism of the alteration in insulin signaling in the liver has been intensively investigated using a number of experimental animal models of obesity and/or hepatic steatosis." (PMID 29717275, 2018). "In line with this contention, the present study confirmed a higher frequency of hepatic steatosis among the insulin-resistant T2D compared to insulin-sensitive CON." (PMID 29914103, 2018). "This uncomplicated exercise intervention improved fat-free mass and muscle mass, hepatic steatosis grade, mean insulin and ferritin levels, and the homeostasis model assessment-estimated insulin resistance index." (PMID 29789470, 2018). "The lower body weight results in beneficial metabolic effects including improved insulin sensitivity, reduced hepatic steatosis and lower WAT inflammation." (PMID 29987474, 2018). "It is well-established that disruption of the hepatic fatty acid oxidation, lipogenesis, and insulin signaling pathways contributes to hepatic steatosis." (PMID 30510243, 2018). "The results showed that paeoniflorin significantly decreased serum insulin and glucagon levels, improved insulin sensitivity and serum lipids profiles, and alleviated hepatic steatosis in fructose-fed rats." (PMID 30081580, 2018). "For instance, a well‐established fibrate, WY14643 (pirinixic acid), decreases plasma triglycerides, reduces adiposity and improves hepatic steatosis and insulin sensitivity in lipoatrophic mice." (PMID 29790245, 2018). "Restoration of liver Ces2c expression in these models ameliorated obesity and liver steatosis, and improved glucose tolerance and insulin sensitivity, while inactivation of Ces2c in mice induced liver steatosis and liver damage." (PMID 28677105, 2018). "In vivo, hepatic Aloxe3 expression enhanced insulin sensitivity, attenuated weight gain, and reduced hepatic steatosis in both diet- and genetically induced steatosis models." (PMID 30135298, 2018). "In another mouse study, long-term feeding with high MCT doses led to liver steatosis, marked lipogenesis, and downregulation of β-oxidation markers, as well as mild improvement of both body mass and insulin sensitivity." (PMID 30208604, 2018). "High level of NEFAs caused lipotoxicity and impaired fatty acid oxidation in mitochondria affects mitochondrial function, contributes to fat accumulation and hepatic steatosis and correlates with impaired insulin signalling." (PMID 29602237, 2018). "In conclusion, we showed that lobeglitazone conferred potentially beneficial effects on insulin sensitivity and hepatic steatosis through improvement of lipid metabolism via altering the expression of target genes involved in these pathways." (PMID 30008738, 2018). "The phosphorylation levels of Akt and GSK3β were significantly decreased in the cows with fatty liver, which further indicated that cows with fatty liver exhibited impaired insulin signaling." (PMID 29882814, 2018). "Altogether, AE mice display protected insulin production from pancreatic islet cells but develop more severe hepatic steatosis." (PMID 29892281, 2018). "Mice overexpressing ApoC-III develop hypertriglyceridemia and diet-induced hepatic steatosis and hepatic insulin resistance." (PMID 29847555, 2018). "Body weight gain, lipid metabolic disorder, and hepatic steatosis as well as systemic and hepatic insulin sensitivity in ob/ob mice were significantly attenuated after sitagliptin treatment." (PMID 30123267, 2018). "It should be noted that genetic disruption of both 12-LOX and 15-LOX in multiple diabetic models largely recapitulates the Aloxe3-mediated enhancement of hepatic insulin sensitivity and reduced hepatic steatosis." (PMID 30135298, 2018).
Hepatic steatosis (continued). "According to the “two hit” theory, fructose contributes to liver steatosis by promoting insulin resistance and liver de novo lipogenesis during the “first hit” and triggering inflammatory and oxidative stress processes during the “second”." (PMID 29534506, 2018). "In this regard, it is of interest that the study participants with hepatic steatosis were insulin resistant, but had higher plasma TG and uric acid concentrations than those without hepatic steatosis." (PMID 28264429, 2017). "Female 5αR1-KO mice aged 6 months were overweight, with impaired insulin sensitivity and hepatic steatosis and this progressed further by 1 y." (PMID 27647861, 2017). "Accordingly, it has been shown that a diet enriched in n-3 PUFA reduces the accumulation of hepatic TGs, restores insulin sensitivity, and ameliorates liver steatosis and the level of hepatic biomarkers (ALT, AST, and GGT)." (PMID 29057834, 2017). "Visceral fat browning in obese mice under freezing low temperature had a global functional impact on improving thermogenic metabolism, insulin sensitivity, and liver steatosis." (PMID 28239649, 2017). "Lactobacillus and Bifidobacterium, as probiotics, diminished body weight gain and macrophage penetration into epididymal fatty tissues, clearly enhanced glucose-insulin homeostasis, and improved hepatic steatosis." (PMID 28086768, 2017). "Similar to our observation, liver X receptors knockout ob/ob mice remain obese but show reduced hepatic steatosis and improved insulin sensitivity." (PMID 29254175, 2017). "Polarization of macrophages to M1 phenotype contributes to imbalance between VAT lipogenesis and lipolysis in favor of the latter, as well as to hepatic steatosis, both being driven by inflammation mediated insulin resistance." (PMID 28993702, 2017). "Of note, obese mice showed improved glucose clearance, insulin sensitivity, and liver steatosis under extremely cold conditions." (PMID 28239649, 2017). "We show here that 7-week-old male mice treated with an Ilex latifolia Thunb supplement for 14 weeks were resistant to HFD-induced body weight gain and hepatic steatosis, accompanied by improved insulin sensitivity." (PMID 29116160, 2017). "This response is characterized by the presence of larger adipocytes in visceral fat tissue, increased hepatic steatosis, as well as reduced glucose tolerance and attenuated insulin responses." (PMID 28771229, 2017). "Overexpression of acid ceramidase upstream of S1P appears to have the same effect within adipose tissue in preventing hepatic steatosis and systemic insulin resistance." (PMID 28271029, 2017). "Pioglitazone, exhibiting dual PPARα/PPARγ agonist, has been established to improve insulin sensitivity and attenuate hepatic steatosis in human studies." (PMID 28831172, 2017). "Usually, hepatic steatosis and glucose production are increased and considered to be detrimental in insulin-resistant animals and humans." (PMID 29254175, 2017). "In particular, we explored the effects of PF on improving fatty liver and IR in NAFLD rats based on its effects on the lipid metabolism-associated regulators and insulin-associated IRS/Akt/GSK3β pathway." (PMID 28300221, 2017). "In comparison to controls, obese PWS showed lower values of FFM (p < 0.0001) and higher FM (p = 0.01), while harbouring higher HDL cholesterol, lower triglycerides and OGTT-derived insulin levels, as well as a lower prevalence and severity of liver steatosis." (PMID 28600576, 2017). "Adenoviral-mediated over-expression of ChREBP in liver of mice improves insulin sensitivity when fed a high-fat diet despite worsened hepatic steatosis." (PMID 29107286, 2017). "This then contributes to the development of hepatic steatosis and deterioration of hepatic insulin sensitivity." (PMID 28466852, 2017).
Hepatic steatosis (continued). "Palmitoleate was able to improve systemic insulin-sensitivity, induce hepatic steatosis, but improve insulin signaling in the liver with a significant increase in insulin-stimulate Akt (Ser 473) phosphorylation." (PMID 29065507, 2017). "Liver steatosis is characterized by excess triglyceride accumulation in liver, leading to hepatocytes being less sensitive to insulin." (PMID 28452943, 2017). "We previously reported an Ath+HF diet mouse model that develops hepatic steatosis, inflammation, fibrosis, and insulin resistance, accompanied with cellular ballooning, a necessary histological feature defining human NASH." (PMID 28591717, 2017). "Similar to our findings, IRF7 knockout improved glucose homeostasis and insulin sensitivity and ameliorated diet-induced hepatic steatosis." (PMID 29254175, 2017). "NOD/SCID HFD-fed mice also developed symptoms of metabolic disturbance, including increased plasma insulin, insulin resistance, hepatic steatosis, and increased adipocyte size, however, these changes were more pronounced in HFD-fed Rag1−/− mice." (PMID 28352127, 2017). "Hepatic steatosis was attenuated by TM5441 along with improvement of hepatic insulin sensitivity presented by decreased p-JNK along with increased p-Akt and p-GSK3β." (PMID 29163785, 2017). "In contrast to simple chronic hepatitis B, concurrence of chronic hepatitis B and hepatic steatosis demonstrates a significant impact on both insulin sensitivity and glucose metabolism." (PMID 28695131, 2017). "Studies on animals highlighted that EGCG was able to prevent obesity by stimulating the mitochondrial complex chain, thereby contributing to the prevention of hepatic steatosis and improved insulin sensitivity." (PMID 29057834, 2017). "Aqueous extract of Ilex latifolia Thunb prevented body weight gain and hepatic steatosis, enhanced insulin sensitivity and reduced chronic inflammation in mice." (PMID 29116160, 2017). "Oral administration of hemin decreases body weight, energy intake, blood glucose and triglyceride levels, and improves insulin and glucose tolerance as well as hepatic insulin signaling and hepatic steatosis in male mice fed a high-fat diet." (PMID 28933767, 2017). "While the search for new drugs to treat T2D and fatty liver disease continues, one intervention that also improves insulin resistance and decreases fatty liver is physical exercise." (PMID 28271029, 2017). "Hepatocyte-specific disruption of CD36 attenuates fatty liver disease and improves insulin sensitivity in HFD-fed mice." (PMID 28578672, 2017). "In four large human trials, rimonabant reduced weight and reduced liver steatosis and insulin sensitivity, data in accord with the reduction in ALT seen in this study." (PMID 28705172, 2017). "In the insulin-resistant state, serum concentrations of FFAs are elevated and have an important role in liver steatosis." (PMID 26731267, 2016). "Although treatment with both GC-1 as well as KB2115 resulted in a decrease of hepatic steatosis, the effects on glycaemia and insulin sensitivity were variable and time-, dosage- and agent-dependent." (PMID 26886134, 2016). "Both diets resulted in hepatic steatosis yet had dramatically different effects on insulin signalling in liver, WAT and muscle." (PMID 27992582, 2016). "It has been shown that the beneficial effects on hepatic steatosis and adipose tissue insulin sensitivity by supplementing ob/ob mice with ω3-PUFAs were due to increased levels of protectin D1 and resolvin D1." (PMID 27999451, 2016). "Animal experiments have illustrated the protective effects of n-3 PUFAs against NAFLD such as reducing hepatic steatosis and improving insulin sensitivity." (PMID 27051672, 2016). "This will further decrease the circulating insulin levels, which would result in reduced lipid synthesis and storage via Irs1 signalling, leading to the improvement of the hepatic steatosis." (PMID 27708333, 2016).
Hepatic steatosis (continued). "Hyperphagia related excessive caloric consumption, adipose tissue lipolysis activation, and hepatic insulin resistance all contribute to hepatic steatosis, while gut-source endotoxins and proinflammatory cytokines are associated with hepatic inflammation." (PMID 27051672, 2016). "Physical activity correlates inversely with hepatic steatosis, independently of changes in body weight or dietary intake, increases insulin sensitivity and reduces central obesity, even in the absence of dietary alteration." (PMID 27314342, 2016). "Fat-specific protein 27 (FSP27)/cell death-inducing DFF45-like effector-C (CIDEC) and lipid storage droplet protein 5 (LSDP5), two members of the LDAP family of proteins, have been shown to facilitate liver steatosis and regulate insulin sensitivity." (PMID 26770990, 2016). "This is in agreement with our data that showed liver-specific knockout of Mfn2 in mice is linked to impaired glucose metabolism, to decreases in SIRT1, SIRT3, and insulin signaling resulting in hepatic steatosis." (PMID 28097021, 2016). "The reduced circulatory insulin inhibited expressions of lipogenic genes in the liver and epididymal fat, leading to decrease in hepatic steatosis and epididymal fat mass." (PMID 26732252, 2016). "Although PTEN-knockout mice gained more weight and adipose tissue during HFD feeding, they showed enhanced insulin sensitivity, improved hepatic steatosis, and reduced adipose tissue inflammation." (PMID 26977813, 2016). "Experimental mice who have undergone PPARα knock-out develop marked hepatic steatosis after being exposed to a high fat diet, and after fasting demonstrate hypoglycaemia and increased insulin sensitivity." (PMID 26978356, 2016). "Numerous studies have shown that even a moderate reduction in weight, 5% in steatosis and 10% in NASH, has the potential to reduce hepatic steatosis, improve insulin sensitivity and significantly improve clinical outcomes in adults." (PMID 27314342, 2016). "A growing body of literatures show that exogenous FGF21 administration improve glucose and lipid homeostasis, insulin sensitivity and hepatic steatosis." (PMID 26914024, 2016). "In NAFLD, several studies have shown a benefit of omega-3 fatty acid treatment on lipid profile, insulin-sensitivity and hepatic steatosis and it has also been suggested that Vitamin D treatment has potential antifibrotic properties in liver disease." (PMID 27977757, 2016). "They observed that rats that were fed a 3 day high-fat diet developed marked hepatic steatosis and hepatic insulin resistance as determined by hyperinsulinaemic-euglycaemic clamp studies." (PMID 26978356, 2016). "Here, the authors show that TRAF3 is upregulated in the liver in non-alcoholic fatty liver disease, promoting insulin resistance, inflammation and hepatic steatosis via its interaction with the kinase TAK1." (PMID 26882989, 2016). "All of which have been shown to be effective in reducing weight gain, body fat, adipocyte size, insulin resistance and hepatic steatosis." (PMID 27023533, 2016). "Subcapsular hepatic steatosis has been exclusively described in patients with continuous ambulatory peritoneal dialysis and those on intraperitoneal insulin, except for one pediatric case, which was probably due to incorrect insulin administration." (PMID 27998312, 2016). "MES + HS treatment (when all three groups were combined), significantly improved visceral adiposity, glycemic control, insulin resistance, systemic inflammation, renal function, hepatic steatosis and lipid profile compared to baseline." (PMID 27759092, 2016). "Increased ChREBP expression in liver results in increased hepatic steatosis, and the isoform ChREBPβ in adipose tissue can predict insulin sensitivity in obese humans." (PMID 27992582, 2016). "Dietary overload of toxic, free metabolic intermediates leads to disrupted insulin signalling and fatty liver disease." (PMID 27320682, 2016).
Hepatic steatosis (continued). "Pathway analysis showed significant role of insulin in development of disease and closed relationship between the highlighted biomarker panel and fatty liver disease." (PMID 28224024, 2016). "The GLP-1 receptor is present on human hepatocytes and has been shown to play a direct role in decreasing hepatic steatosis in vitro by modulating components of the insulin signaling pathway." (PMID 26191473, 2015). "Even in mice on standard laboratory chow, continuous subcutaneous infusion of low-dose LPS results in hepatic steatosis, hepatic insulin resistance and hepatic weight gain." (PMID 26629827, 2015). "Meanwhile, the accumulation of lipid in skeletal muscle, albeit slower than the development of hepatic steatosis, is nevertheless accompanied by a reduction in insulin-stimulated glucose disposal." (PMID 26236747, 2015). "Fasting blood glucose and insulin levels as well as glucose tolerance testing are necessary to assess the involvement of the changes of insulin sensitivity in the deterioration of hepatic steatosis in this animal model." (PMID 26581663, 2015). "Here, we report that class II PI3K-C2β kinase-dead mice are viable and healthy but display an unanticipated enhanced insulin sensitivity and glucose tolerance, as well as protection against high-fat-diet-induced liver steatosis." (PMID 26655903, 2015). "Specifically, carnitine or carnitine-orotate complex, which promotes fatty acid β-oxidation, improves insulin sensitivity or attenuates hepatic steatosis in most randomized clinical trials." (PMID 26613076, 2015). "While somewhat exceptional, we are aware of several reports where the ablation of proteins involved in triglyceride synthesis prevented the onset of fatty liver but also coincided with reduced insulin sensitivity or glycemic control." (PMID 25849936, 2015). "A recent study, which also explored the effect of TR agonists on hepatic steatosis, found that GC-1, despite reducing hepatic triglyceride content, reduced whole body insulin sensitivity in rats by increasing hepatic glucose production." (PMID 25849936, 2015). "An excess of glucose, fatty acid, and insulin ultimately leads to hepatic steatosis and worsening of hepatic IR." (PMID 26438035, 2015). "The benefits included weight loss, fat mass reduction, improved glucose tolerance, improved insulin sensitivity and resolution of liver steatosis." (PMID 26197299, 2015). "Among them, valproate has been shown to attenuate atherosclerosis and alleviate hepatic steatosis and azoramide has been shown to improve insulin sensitivity and pancreatic β-cell function in rodent models." (PMID 26613076, 2015). "Chronic treatment of obese rodents with FGF21 reduced hepatic steatosis and improved insulin sensitivity, indicating that FGF21 treatment also improves liver function." (PMID 26834701, 2015). "Our study uncovered that kinase inactivation of PI3K-C2β in mice enhances insulin sensitivity and protects against high-fat-diet-induced hepatic steatosis." (PMID 26655903, 2015). "Intriguingly, hepatic overexpression of Gadd34, which encodes an eIF2α-specific phosphatase that selectively counteracts PERK-eIF2α action, results in improved insulin sensitivity and diminished hepatic steatosis on HFD." (PMID 26613076, 2015). "Treated mice also had a more favorable metabolic profile, with lower levels of circulating leptin and insulin, and improved glucose tolerance and insulin sensitivity, along with reduced hepatic steatosis and inflammation." (PMID 25825594, 2015). "The acute challenge of insulin or leptin also confirms lowered insulin and leptin sensitivity occurred during the development of hepatic steatosis upon HFHS dieting, further verifies the existence of impaired signaling transduction." (PMID 25658428, 2015). "The relationship between fatty liver and elevated fasting circulating levels of glucose and insulin has been reported in cross-sectional studies." (PMID 26714769, 2015).